CDK7 (cyclin dependent kinase 7)
Diseases named in the same sentence as CDK7 in open-access papers (continued):
Sharing a sentence is not in itself a finding about the gene and the disease.
breast carcinoma (continued). "We show that both HER2 inhibitor-sensitive (HER2iS) and HER2iR breast cancer cell lines exhibit high sensitivity to THZ1, a newly identified covalent inhibitor of the transcription regulatory kinase CDK7." (PMID 31462705, 2020). "We investigated correlations between CDK7 RNA expression and relapse-free survival (RFS) in breast cancer using a microarray database of 3,951 breast cancer patients." (PMID 32155786, 2020). "CDK7, Cyclin H, and MAT1 protein and mRNA expression were found to be upregulated in breast cancer tumors, compared to matched adjacent normal breast tissue, particularly in ER+ breast cancer." (PMID 32155786, 2020). "In analogy, we identified MYC enrichment at the identical site in the CDK7 promoter in various ChIP-seq data sets from breast cancer and B-cell malignancies suggesting that both MITF and MYC are able to directly transactivate CDK7." (PMID 30651597, 2019). "As a pioneer factor for ER in breast cancer cells, the potent inhibition of GATA3 expression by CDK7 inhibitors provides further evidence for its potential utility in the treatment of ER-positive breast cancer." (PMID 27748765, 2017). "Our data showed that Nar differentially downregulated the expression of Cdk4, Cdk6, and Cdk7 in the human colorectal cancer cell lines SW1116 and SW837 and in the human breast cancer cell lines HTB26 and HTB132." (PMID 26074733, 2015). "In this study, by integrating CRISPR-CAS9 functional genomics (DEPMAP database) and TCGA multi-omics data, seven key genes (CDK7, CLTC, COPB2, CRNKL1, GSPT1, NSF and PSMD12) that are closely related to the proliferation and prognosis of breast cancer were systematically identified." (PMID 40657358, 2025). "CDK7 regulates cell cycle progression through transcriptional control rather than direct phosphorylation, making it a promising target in HER2 inhibitor-resistant breast cancer." (PMID 39806366, 2025). "Experimental approaches targeting CDK7 through specific small molecular inhibitors, such as THZ1, LDC4297, ICEC0942, SNS-032, and roscovitine, have proven effective in suppressing ER+ breast cancer cells." (PMID 38605321, 2024). "One study, utilizing publicly available transcriptomic data from a specific group of TNBC patients (n = 383) and the METABRIC TNBC dataset (n = 217), identified that elevated CDK7 mRNA levels were synonymous with reduced relapse free survival (RFS) and poor breast cancer specific survival (BCSS)." (PMID 38605321, 2024). "In addition, inhibitors of CDK7, a cyclin-activating kinase, CDK2 and CDK2/4/6 inhibitors are in clinical development in ER+ breast cancer." (PMID 37921419, 2023). "CDK8, CDK7, CDK4, and CDK1 predicted unfavorable outcomes in luminal A breast cancer patients." (PMID 35628286, 2022). "Ongoing phase I trials are investigating the efficacy of the CDK7 inhibitors SY-1365 and CT-7001 combined with fulvestrant in patients with solid tumors, including ER+/HER2− breast cancer patients who progressed on CDK4/6i-based therapy (NCT03134638, and NCT03363893)." (PMID 34771560, 2021). "Our results indicate that CDK7, CDK8, and CDK13 could be prognostic biomarkers for breast cancer patients." (PMID 33686962, 2021). "Other experiments have shown that no apparent selectivity between different subtypes of breast cancer under CDK7 treatment was detected." (PMID 34109118, 2021). "However, we also found strong positive correlations between CDK7 RNA expression and survival in both luminal B (rapidly growing ER+) and HER2+ breast cancer patients, the HER2+ findings consistent with a recent report." (PMID 32155786, 2020).
breast carcinoma (continued). "Triple-negative breast cancers (TNBC) but not estrogen receptor-positive (ER+) breast cancers have been reported to be uniquely sensitive to the CDK7 inhibitor THZ1 due to the inhibition of a cluster of TNBC-specific genes." (PMID 32155786, 2020). "Breast cancer cells with acquired resistance to palbociclib remain sensitive to THZ1, suggesting that CDK7 inhibitors may be useful following the onset of resistance to drugs that target other CDKs." (PMID 32385714, 2020). "Our finding that both HER2 inhibitor-sensitive and -resistant breast cancer cell lines became highly sensitized to THZ1 and exhibited a similar response to THZ1 to that of TNBC, could be attributed to CDK7-dependent transcriptional inhibition." (PMID 31462705, 2020). "Of special interest, CDK7 has been identified as a promising therapeutic target in TNBC, which was reported to be especially sensitive to THZ1 among the principal molecular subtypes of breast cancer." (PMID 32155786, 2020). "Furthermore, CDK7 inhibitors can impede the activation of genes regulated by multiple HER2 inhibitor-resistant kinases, offering an alternative therapeutic approach to reverse acquired resistance in HER2-positive breast cancer." (PMID 40949156, 2025). "Furthermore, we identified extensive transcriptional disruption, rather than solely CDK7 inhibition, as the mechanism underlying the nutlin-3 and THZ1-induced death of breast cancer cells." (PMID 36058938, 2022). "In breast cancer models, the EGFR inhibitor erlotinib displayed synergy with THZ1 and with the dual cdc7/CDK9 inhibitor PHA-767491, with more lines of evidence suggesting CDK7 and CDK9 inhibitors could sensitise resistant cancer cells to EGFR-targeted therapy." (PMID 35568739, 2022). "Hence, other factors not specifically related to breast cancer molecular subtype influence sensitivity to CDK7 inhibition." (PMID 32155786, 2020). "Our results suggest that EGFR and CDK7 combination therapy may be a novel treatment strategy for breast cancers, regardless of subtype." (PMID 32155786, 2020). "Also, CDK7’s role in overcoming chemotherapeutic resistance in breast cancer was mentioned before, where CDK7 inhibition by TZH1 was found to reverse the resistant in HER2+ breast cancer patients." (PMID 32340192, 2020). "The involvement of CDK7 and CDK9 revealed here in regulating H1.4-S187 phosphorylation may contribute to the unique requirement of H1.4 among H1.0 and H1.1-H1.5 for the viability of human breast cancer cells." (PMID 28539972, 2017). "Additionally, Nar altered the expression of apoptosis and cell-cycle regulatory genes by down-regulating Cdk4, Cdk6, Cdk7, Bcl2, x-IAP and c-IAP-2 and up-regulating p18, p19, p21, caspases 3, 7, 8 and 9, Bak, AIF and Bax in both colorectal and breast cancer cells." (PMID 26074733, 2015). "However, CDK7 expression did not exhibit prognostic significance in the remaining breast cancer subtypes, indicating the prognostic value of CDK7 may be restricted to TNBC." (PMID 39656925, 2025). "The results showed that although the mRNA expression of CDK7, CDK8, CDK19, and CDK20 was higher in breast cancer tissues, none of these transcripts’ values reached statistical significance." (PMID 33686962, 2021).
breast carcinoma (continued). "Indeed, in vitro kinase assays using purified components and 10 μM ATP showed that CRAF efficiently phosphorylates purified CDK4 at T172, whereas CDK7 and c-Jun N-terminal kinase (JNK) were excluded as relevant CAKs in the context of NF1-depleted ER+ breast cancer." (PMID 41226361, 2025). "CDK7 inhibitor can strongly diminish the transcription of a cluster of particular genes, which are overexpressed in TNBC but not in hormone receptor (HR)+ breast cancer cells containing putative oncogenes, promoting TNBC tumorigenicity and the disease development." (PMID 32398735, 2020).
neuroblastoma (30 papers, 2016 to 2025). Neuroblastoma (NB) is the most common solid, extracranial childhood tumor. "CDK7 phosphorylates serine 5 of Pol2 at the promoter to promote initiation, and it has been shown that CDK7 inhibitors have a synergistic effect when combined with BRD4 inhibitors in neuroblastoma, so a local increase in CDK7 could also be implicated." (PMID 37259348, 2023). "Previous studies demonstrated that the anticancer efficacy of CDK7 inhibitors was associated with CDK7-dependent transcriptional addiction in small cell lung cancer and ovarian cancer and super-enhancer-associated genes in neuroblastoma and oesophageal squamous cell carcinoma." (PMID 31076643, 2019). "An alternative strategy to lower MYCN levels involves targeting cyclin-dependent kinase 7 (CDK7) to interfere with the transcription of amplified MYCN in neuroblastoma cells." (PMID 40365336, 2025). "PKC-ι promotes cell proliferation in neuroblastoma cells through the PKC-ι/cyclin dependent kinase (Cdk7)/Cdk2 pathway." (PMID 36776326, 2023). "Another approach to interfere with neuroblastoma growth is the inhibition of cyclin-dependent kinase 7 (CDK7) by the covalent inhibitor THZ1." (PMID 35681734, 2022). "THZ1, a CDK7 inhibitor, exerts synergistic anticancer effects when combined with TKIs against neuroblastoma, glioma and non-small cell lung cancer." (PMID 36076237, 2022). "Here we determined the effects of YKL-5-124, a novel covalent inhibitor with greater selectivity for CDK7 in neuroblastoma cells." (PMID 35198433, 2021). "It has been demonstrated that genomic amplification of the MYCN oncogene by promoting SEs causes upregulation of the active transcriptional program of neuroblastoma (NB) cells and sensitizes NB cells to the inhibition of CDK7." (PMID 32128448, 2020). "The CDK inhibitor SNS-032 had previously exerted promising anti-neuroblastoma activity via CDK7 and 9 inhibition." (PMID 27517323, 2016). "The CDK7-dependent transcriptional addition reported in MYCN-driven neuroblastoma, triple-negative breast cancer, and pancreatic cancer is attractive because SE-associated genes are exceptionally inhibited by THZ1 so that targeting CDK7 is conducive to selective targeting." (PMID 33397398, 2021). "We have found that the JMJD6 gene is associated with transcriptional super-enhancers in JMJD6 gene-gained neuroblastoma cells, and that treatment with the CDK7 inhibitor THZ1, which specifically targets super-enhancer associated oncogenes, significantly reduces JMJD6, N-Myc, and c-Myc expression." (PMID 31346162, 2019). "Based on this, it was hypothesized that disrupting the CRC and transcriptional initiation and elongation through BRD4 and CDK7 inhibition may be an effective strategy for treating neuroblastoma." (PMID 30326621, 2018). "Finally, inhibition of CDK7, a transcriptional cyclin-dependent kinase which functions downstream of MYC and is MYC’s 10th-ranked correlation, causes marked regression of aggressive, MYC-driven neuroblastomas in mice." (PMID 33328249, 2021). "Recent studies demonstrated that YKL-5-124, a novel covalent CDK7 inhibitor, combined with JQ1, induced synergistic cytotoxicity in vitro and significant tumor regression in patient-derived xenograft neuroblastoma models." (PMID 40365336, 2025). "THZ1, a covalent CDK7/12/13 inhibitor, exerts antitumor activity through transcriptional regulation by inhibiting CDK7 in acute T cell leukemia, MYCN-amplified neuroblastoma, small cell lung cancer, and triple-negative breast cancer." (PMID 37342192, 2023). "SCLC is sensitive to THZ1, a covalent CDK7 inhibitor with single-agent activity in T-cell acute lymphoblastic leukemia, MYCN- dependent neuroblastoma, and triple-negative breast cancer." (PMID 36163484, 2022). "Subsequently, other transcriptionally addicted malignancies, including MYCN-amplified neuroblastoma and MYC/MYCL-amplified SCLC showed also sensitivity to CDK7 inhibition." (PMID 33686962, 2021).
neuroblastoma (continued). "A covalent inhibitor of CDK7, THZ1, selectively targets MYCN-amplified neuroblastoma cells, leading to global suppression of MYCN-dependent transcriptional amplification and sustained growth inhibition of tumors in a mouse model of neuroblastoma." (PMID 33614505, 2020). "BRD4 and CDK7 inhibitors synergistically repress the expression of all the CRC transcription factors and N-MYC, which inhibits neuroblastoma cell growth." (PMID 33614505, 2020). "In conclusion, we provide insight into the role of the TBX2 CRC gene in transcriptional dependency of neuroblastoma cells warranting clinical trials using BET and CDK7 inhibitors." (PMID 30451831, 2018). "The effects of combined BRD4 and CDK7 inhibition on both CRC and global gene expression were evaluated in neuroblastoma cell lines." (PMID 30326621, 2018). "Interference with CDK7 and CDK9 appeared to be critical for the anti-neuroblastoma effects of SNS-032." (PMID 27517323, 2016). "The CDK7 inhibitor THZ1 is highly effective in targeting models of c-Myc-driven small cell lung carcinoma, neuroblastoma and triple-negative breast cancer." (PMID 27756891, 2016). "This specific resistance to RNA polymerase inhibition via interference with CDK7 and 9 also confirms CDK7 and 9 as critical drug targets of SNS-032 in neuroblastoma that was previously suggested." (PMID 27517323, 2016). "CDK7 and 9 play critical roles in transcription initiation and elongation and expression of both was decreased with treatment of UKF-NB-3 and IMR-32 neuroblastoma cells with SNS-032." (PMID 26771642, 2016). "THZ1, a covalent CDK7 inhibitor, effectively downregulated MYCN expression, resulting in significant tumor regression in a high-risk neuroblastoma mouse model without inducing systemic toxicity or off-target effects." (PMID 40365336, 2025). "We focused on the ALK, IGF1, WNT, EZH2/PRC2, BET, CDK7, and CDK12/13 signaling pathways since they have been shown to be important during the normal development of sympathoadrenal cells and/or involved in neuroblastoma tumorigenesis." (PMID 35681734, 2022). "Indeed, specific subgroups of patients are more dependent on CDK7 (triple-negative breast cancer) and/or CDK9 (MYC-driven neuroblastoma)." (PMID 34344865, 2021). "The combination of CDK7 and BRD4 inhibition provides a therapeutic option for neuroblastoma and suggests that the addition of YKL-5-124 could improve the therapeutic efficacy of JQ1 and delay resistance to BRD4 inhibition." (PMID 35198433, 2021). "A specific inhibitor targeting CDK7, THZ1, has also been examined in neuroblastoma." (PMID 26771642, 2016). "While THZ1 appears to preferentially affect genes controlled by super-enhancers in neuroblastoma, MYCN-dependent genes in particular, there is evidence to indicate that the off-target inhibition of CDK12 and CDK13 rather than of CDK7 is responsible for the transcriptional effects of THZ1." (PMID 35681734, 2022).
prostate carcinoma (24 papers, 2017 to 2025). A carcinoma that arises from epithelial cells of the prostate gland. "It inhibits the phosphorylation of AR and its castration-resistant variant AR-V7 at Ser515 via XPB/CDK7, enhancing the anti-prostate cancer activity of enzalutamide in castration-resistant prostate cancer." (PMID 41278192, 2025). "Men carrying the homozygous wild-type TT genotype at two correlated CDK7 SNPs, rs11744596 and rs2932778, were at increased risk of developing prostate cancer after exposure to carbofuran." (PMID 36908412, 2023). "CT7001 selectively engages with CDK7 in prostate cancer cells, causing inhibition of proliferation and cell cycle arrest." (PMID 37076563, 2023). "Moreover, lncRNA SNHG1 negatively regulates miR-199a-3p to enhance CDK7 expression and promote cell proliferation in prostate cancer and can serve as diagnostic and prognostic markers for prostate cancer through androgen-responsive manner." (PMID 29340086, 2017). "Additionally, lycopene could alleviate the prostate cancer risk by modulating the growth genes like cyclin-dependent protein kinase 7 (CDK7), B-cell lymphoma 2 (BCL2), epidermal growth factor receptor (EGFR), and insulin-like growth factor 1 (IGF-1) receptor." (PMID 40013157, 2025). "Particularly intriguing are preclinical prostate cancer models where CDK7 inhibition with the newly identified inhibitor THZ1 attenuates AR signaling and eradicates hormone-sensitive and enzalutamide refractory prostate cancer cells." (PMID 40075623, 2025). "This complements published studies using cell-free in vitro kinase assays and confirms CT7001’s potent and selective pharmacology against CDK7 in living prostate cancer cells." (PMID 37076563, 2023). "Overexpression of CDK7 and its positive regulators implies that increased activity of this kinase is beneficial for prostate cancer cells." (PMID 36401094, 2023). "First, we show that CDK7 and its positive regulators are overexpressed in aggressive prostate cancer." (PMID 36401094, 2023). "There are reasons to think that targeting this pathway may be particularly well suited to prostate cancer patients, given that CDK7-mediated activation of the mediator complex enhances androgen receptor transcription factor activity." (PMID 40075623, 2025). "We hypothesized that the aggressive prostate cancer cells would upregulate CDK7 and its positive regulators, because this kinase is involved in two processes essential for the rapid proliferation: transcription and the cell cycle." (PMID 36401094, 2023). "Here, we show that also the binding partners of CDK7 are overexpressed in prostate cancer." (PMID 36401094, 2023). "Indeed, CDK7 expression was significantly higher in the prostate cancer tissue when compared to the normal tissue." (PMID 36401094, 2023). "A previous report showed that lncRNA SNHG1 serves as a ceRNA to negatively regulate miR-199a-3p and enhance CDK7 expression, which might be a potential therapeutic target for prostate cancer." (PMID 31269941, 2019). "First, we treated prostate cancer cells for four hours with increasing doses of the highly specific inhibitor against each kinase, to establish doses that robustly decrease RNA Pol II phosphorylation: 500 nM for CDK7 and CDK12/13 inhibitors and 20 nM for CDK9 inhibitor were found to achieve this." (PMID 35164752, 2022). "SNHG1 via regulating miR-199a-3p/CDK7 axis could promote cell proliferation in prostate cancer." (PMID 33330110, 2020). "For example, CDK7 is an important regulator of both factors, at least in part because it phosphorylates MED1 to enhance AR- and MYC-regulated transcription in prostate cancer." (PMID 40163908, 2025). "For example, CDK7 phosphorylates Threonine 1457 (T1457) of the Mediator Complex Subunit 1 (MED1), which is upregulated in prostate cancer cells." (PMID 40163908, 2025).